GCLC (glutamate-cysteine ligase catalytic subunit)
Description:
Catalyzes the ATP-dependent ligation of L-glutamate and L-cysteine and participates in the first and rate-limiting step in glutathione biosynthesis.
Synonyms: GLCL; GLCLC; GCS; CNSHA7; GCL
Tractability: Small molecule: it belongs to a druggable protein family. PROTAC: ubiquitination databases record sites on it; its protein half-life has been measured; a small molecule that binds it is known.
Target class: Enzyme; Ligase
Safety:
Unwanted effects reported when the protein is acted on. In parentheses: how it was acted on, where the effect was seen, and who reports it.
a drug hypersensitivity reaction (source: ClinPGx)
Gene: Protein-coding gene on chromosome 6 (53,497,341 to 53,616,970, reverse strand). Ensembl gene ENSG00000001084.
Subcellular location (Human Protein Atlas): Nucleoplasm; Cytosol; Nucleoli
Pathways (Reactome):
Cellular responses to stimuli: NFE2L2 regulating anti-oxidant/detoxification enzymes
Disease: Defective GCLC causes HAGGSD
Metabolism: Glutathione synthesis and recycling
Gene Ontology:
Molecular function: ADP binding; glutamate binding; glutamate-cysteine ligase activity; magnesium ion binding; protein binding; catalytic activity
Biological process: blood vessel diameter maintenance; cell redox homeostasis; glutamate metabolic process; glutathione biosynthetic process; negative regulation of apoptotic process; negative regulation of DNA-templated transcription; response to heat; response to hormone; response to oxidative stress; cellular response to fibroblast growth factor stimulus; cellular response to follicle-stimulating hormone stimulus; cellular response to glucose stimulus; cellular response to hepatocyte growth factor stimulus; cellular response to insulin stimulus; cellular response to mechanical stimulus; cellular response to thyroxine stimulus; negative regulation of hepatic stellate cell activation; negative regulation of neuron apoptotic process; response to activity; response to cadmium ion; response to human chorionic gonadotropin; response to interleukin-1; response to nitrosative stress; response to nutrient
Cellular component: glutamate-cysteine ligase complex; cytosol
Genetic constraint (gnomAD): Loss-of-function variants: 9 observed, 38.85 expected, observed/expected ratio (o/e) 0.23, 90% interval 0.14 to 0.4. The upper end of that interval is the gene's LOEUF score, 0.4, which puts it in group 1 of 6, group 1 being the genes least tolerant of losing a copy. Missense variants: 319 observed, 444.96 expected, observed/expected ratio (o/e) 0.72, 90% interval 0.65 to 0.79. Synonymous variants: 160 observed, 155.68 expected, observed/expected ratio (o/e) 1.03, 90% interval 0.9 to 1.17.
Homologues: Orthologues: chimpanzee GCLC (99% identical), macaque GCLC (99% identical), dog GCLC (97% identical), rabbit GCLC (97% identical), mouse Gclc (95% identical), rat Gclc (94% identical), guinea pig GCLC (92% identical), pig GCLC (89% identical), tropical clawed frog gclc (85% identical), zebrafish gclc (79% identical), Drosophila melanogaster Gclc (12% identical), Caenorhabditis elegans gcs-1 (9% identical).
Diseases named in the same sentence as GCLC in open-access papers:
GCLC is named in the same sentence as 121 diseases in open-access papers, as found by Europe PMC text mining. Sharing a sentence is not in itself a finding about the gene and the disease. The quoted sentences say what the papers report.
lung carcinoma (22 papers, 2013 to 2025). "GCLC is another tumor suppressor gene that induces synthetic lethality of cancer cells; GCLC deletion is associated with lung cancer development." (PMID 32444802, 2020). "Survival data from male patients with lung cancer showed that mutations in GCLC, and GPX2, key genes in glutathione metabolism, contribute to a bad prognosis." (PMID 32850411, 2020). "Additionally, the GCLC gene, which was found to be hypomethylated in lung cancer samples, has been associated with tumor progression and drug resistance." (PMID 33143142, 2020). "Since existing knowledge underscores the predominant role of GCLC over GCLM in modulating cancer progression, we thereby individually silenced CBS and GCLC in lung cancer cells." (PMID 40885716, 2025). "Given the downregulation of CBS, GCLC, and GCLM in DDX3X-deficient lung cancer cells, we then questioned which enzyme primarily mediates the effects of DDX3X inhibition." (PMID 40885716, 2025). "Melanoma and lung cancers patients suffer from high levels of GCLC as well as elevated enzymatic activity of GCLC in renal cell carcinoma patients." (PMID 33381452, 2020). "Analyzing survival data of men with lung cancer, we observed that patients with mutations in GCL catalytic subunit (GCLC) or Glutathione peroxidase 1 (GPX1) genes survived less time than people without mutations on these genes." (PMID 32850411, 2020). "It is well known that the classic NRF2-regulated gene GCLC (glutamate-cysteine ligase catalytic subunit) is highly expressed in lung cancer and increased GCLC expression is highly correlated with poorer survival." (PMID 29050246, 2017). "Similar reductions in GCLC mRNA were observed in H838 lung cancer cells upon treatment with LINC00942 ASOs." (PMID 28959951, 2016). "In the present work, we evaluated the effect of GCLC siRNA on GNPs-induced cytotoxity in lung cancer cells." (PMID 25789740, 2015). "We observed that GNPs can induce apoptosis and necrosis simultaneously when the GCLC was silenced by siRNA in lung cancer cells." (PMID 25789740, 2015). "The primary objective of this study is to characterize the cytotoxity of GNPs in lung cancer cells when GCLC was knocked down by siRNA." (PMID 25789740, 2015). "GSH and NAC can eliminate the ROS to neutralize the cytotoxicity of GNPs in lung cancer cells transfected with GCLC siRNA." (PMID 25789740, 2015). "Herein, we investigated the cytotoxicity of GNPs toward lung cancer cells under the glutamate cysteine ligase catalytic subunit (GCLC) was silenced by siRNA." (PMID 25789740, 2015). "This study investigated the expression of Nrf2 and of Nrf2-targeted genes (NQO1 and GCLC) and the genes for the metallothionein (MT) isoforms (MT-1A and MT-2A) in human lung cancer and cancer-surrounding tissues." (PMID 23947958, 2013). "Finally, the glutamate–cysteine ligase catalytic subunit (GCLC) can protect against ferroptosis in lung cancer." (PMID 34395526, 2021). "This analysis showed that male bronchus and lung cancer patients with mutations on the GCLC gene survived less time than those without this gene mutated (p-value 0.0183)." (PMID 32850411, 2020). "Conversely, the overexpression of either CBS or GCLC in A549 cells led to accelerated cell proliferation and diminished Fe2+ and lipid peroxidation levels, underscoring the vital roles of these enzymes in modulating antioxidant homeostasis and lung cancer progression." (PMID 40885716, 2025). "YEATS4 amplification samples show increased mRNA levels of several well-known antioxidant genes, including NQO1, SLC7A11, and GCLC, suggesting beside NFE2L2 mutation and KEAP1 mutation, YEATS4 amplification could be the other critical genetic marker in lung cancer by modulating antioxidant pathways." (PMID 38514704, 2024).
lung carcinoma (continued). "GNPs induced apoptosis and necrosis in lung cancer cells due to its cytotoxic effect via increase of intracellular reactive oxygen species (ROS) and regulation of cellular glutathione in lung cancer cells by conjugation with glutamate cysteine ligase catalytic (GCLC-specific siRNA)." (PMID 28240047, 2017). "Treatment of ABC1 and SW900 lung cancer cells, which both contain a functional KEAP1-NRF2 response, resulted in significant induction of NRF2 target gene expression, including NQO1, GCLC, HMOX1 and TXNRD1." (PMID 40890297, 2025). "The decreased transcription of GCLC and GSS through the inhibition of NRF2 emerged as a mechanism of mutant EGFR/T790M resistance to EGFR inhibition in lung cancer." (PMID 39001381, 2024). "As a result of these observations, we postulate that GCLC, GPX1 genes and glutathione metabolism are possible targets to delay EMT or potentially prevent the EMT in lung cancer." (PMID 32850411, 2020). "Compared with A549 or H460 lung cancer cell lines stably transfected with empty vector, mRNA levels of NRF2 and its target genes HO-1, GCLC, and FTH1 were significantly decreased after the cell lines were stably transfected with WT KEAP1." (PMID 32576270, 2020). "However, mRNA levels of NRF2 and its target genes HO-1, GCLC, and FTH1 were significantly increased in the A549 or H460 lung cancer cell lines stably transfected with these five KEAP1 mutants." (PMID 32576270, 2020). "This suggested that GCLC and GPX1 genes may be used as biomarkers of bad prognosis in people with lung cancer, even with different genetic backgrounds." (PMID 32850411, 2020). "Expression of the Nrf2-targed genes NQO1 and GCLC tended to be higher (30 to 60%) in lung cancers, but was not significantly different from that in peri-cancer tissues." (PMID 23947958, 2013). "In addition, overexpression of GCLC mRNA suppresses the expression of MRP1, which in turn could improve the chemosensitivity in lung cancer patients." (PMID 34054937, 2021).
breast carcinoma (14 papers, 2012 to 2025). "We have found an association of the polymorphism rs3736729 on the GCLC gene with breast cancer (OR = 0.85 (95% CI, 0.73–1.00) and p-value = 0.054) in a recessive model." (PMID 23443115, 2012). "Previous data from our group relate the polymorphisms rs1052133 on the OGG1 gene, rs207454 on the XDH gene and rs3736729 on the GCLC gene to susceptibility to breast cancer." (PMID 23443115, 2012). "Thus, to investigate if breast cancer risk factors influence (oxidative) cellular stress, levels of GCLC and PCOXY1 were investigated as dependent variable as well." (PMID 34921608, 2022). "High GCLC expression in breast cancer enhances GSH biosynthesis with a concurrent reduction in intracellular ROS accumulation, thereby provoking reductive stress." (PMID 36359768, 2022). "To assess the possible clinical relevance of NQO1 and GCLC, we determined if their mRNA levels showed any prognostic value in human breast cancer patient cohorts, with long-term follow-up (nearly 20 years)." (PMID 28411284, 2017). "This one is the first study that shows a relationship between polymorphisms on the GCLC and XDH genes and the survival outcome in breast cancer patients." (PMID 23443115, 2012). "Previous studies of our group have associated polymorphisms on genes related to oxidative stress (rs3736729 on GCLC and rs207454 on XDH) and DNA damage repair (rs1052133 on OGG1) with a predisposition to develop breast cancer." (PMID 23443115, 2012). "Furthermore, the mRNA levels of KDM4C and GCLC show a significant positive correlation in basal breast cancer in the TCGA cohort, implying coregulation in clinical samples." (PMID 40457074, 2025). "Moreover, in previous studies, GCLC has been reported to be highly expressed in various types of cancer, such as breast cancer, hepatocellular carcinoma, and colon cancer." (PMID 36359768, 2022). "In breast cancer, GCLC expression was inversely correlated with malignancy." (PMID 27206673, 2016). "Thus, we speculate that pharmacological inhibition of NQO1 and GCLC may be new therapeutic strategies for overcoming tamoxifen-resistance in breast cancer patients." (PMID 28411284, 2017). "Thus, pharmacological inhibition of NQO1 and GCLC may be new therapeutic strategies for overcoming tamoxifen-resistance in breast cancer patients." (PMID 28411284, 2017). "This work suggests that unfavorable genetic variants in the rs207454 (XDH) and rs3736729 (GCLC) polymorphisms may act as predictors of the outcome in negative progesterone receptor and negative estrogen receptor breast cancer patients, respectively." (PMID 23443115, 2012). "Breast cancer CSCs show an increased expression of the NRF2 target gene, glutamate-cysteine ligase catalytic subunit (GCLC)." (PMID 36289675, 2022). "Thus, NQO1 and GCLC may be i) new prognostic biomarkers, ii) novel therapeutic targets and iii) companion diagnostics, for predicting and overcoming tamoxifen-resistance in different subsets of ER(+) breast cancer patients." (PMID 28411284, 2017).
melanoma (12 papers, 2015 to 2026). A malignant, usually aggressive tumor composed of atypical, neoplastic melanocytes. "From a clinical point of view, there is evidence that the high expression of GCLC predicts a better prognosis for melanoma patients." (PMID 32850411, 2020). "The upregulation of CAT, SODs, GPx and glutamate-l-cysteine ligase catalytic subunit (GCLC) in human melanoma biopsies and a large set of melanoma cell lines was demonstrated in a systematic review." (PMID 33091721, 2020). "It has also been determined that melanomas with higher expressions of GCLC correlate with a better prognosis in patients; however, GCLC expression does not necessarily indicate changes in GCL activity, as GCLM expression plays a larger role in controlling the function of GCL." (PMID 35326683, 2022). "A Thai herbal formula (AVS073 formula) was shown to have inhibitory effects on UVA-induced melanogenesis, and this was associated with a redox mechanism involving up-regulation of GSH biosynthesis caused by the increased mRNA expression of GCLC and GCLM in human melanoma cells." (PMID 33871027, 2021). "Besides, GCLC has also been reported as a biomarker of poor survival in melanoma patients, and malignant phenotypes were more prominent in melanoma cells with lower GCLC expression." (PMID 32850411, 2020). "Consistent with previous reports that associated the Nrf2 pathway with SFN-induced chemoprevention, we found that the Nrf2 target genes HMOX1, TXNRD1, GCLC, GCLM, AKR1B10 and G6PD were upregulated after melanoma treatment." (PMID 28864908, 2018). "Inhibition of glutathione synthesis via the GCLC inhibitor buthionine sulfoximine has not been shown to be effective against melanomas in vitro or in vivo; however, in combination with cysteine transport or thioredoxin inhibition, greater efficacy is achieved." (PMID 35326683, 2022). "We did not observe an increase in GCLC mRNA levels in the G-361 melanoma cell line following RTA 408 treatment; the molecular mechanism underlying this is not known." (PMID 25897966, 2015). "Moreover, ERU increased the expression of antioxidant target genes, such as GCLC, GCLM and HMOX-1, suggesting that the modulation of ROS production and the impairment of mitochondrial activity in the melanoma cells were among the contributing factors, which supported the antitumor activity of ERU." (PMID 36670903, 2022). "However, it has also been reported that the expressions of GCLM and GCLC do not correlate with NRF2 expression in melanoma." (PMID 35326683, 2022). "Thus, GCLC and NFE2L1 upregulation in A7 may contribute to both the increased ROS scavenging capacity compared with G10 and controls and its more differentiated and less aggressive melanoma." (PMID 27206673, 2016).
hepatocellular carcinoma (11 papers, 2013 to 2025). A malignant tumor that arises from hepatocytes. "For example, a high level of GCLC is associated with poor prognosis in patients with acute myeloid leukemia and hepatocellular carcinoma." (PMID 36139430, 2022). "Our data suggested that lncGCLC and GCLC were lowly expressed in hepatocellular carcinoma but also positively correlated." (PMID 36851037, 2023). "This study was conducted to investigate whether homocysteine induces the Nrf2 dependent expression of GCLc in hepatoma cell line (HepG2) and whether this induction is mediated by antioxidant response element (ARE) which present within its promoter." (PMID 23967023, 2013). "Since low SOCS1 gene expression correlates with poor prognosis in the TCGA-liver hepatocellular carcinoma (LIHC) dataset, and high GCLC in HCC tissues correlates with poor prognosis, we evaluated the relationship between SOCS1, NFE2L2 (NRF2) and GCLC gene expression in the TCGA-LIHC dataset." (PMID 38254783, 2024). "In mouse hepatoma cells, tert-butylhydroquinone elicited oxidative stress and maximally induced gene expression of GCLM 10-fold, and that of GCLC 2-fold." (PMID 34445563, 2021). "As in mouse cells and tissues, treatment with TBE-31 or the naturally occurring Nrf2 activator sulforaphane (SFN) upregulated the expression of CES1 in the human hepatoma cell line HepG2, which has high basal levels of CES1, in a manner resembling that of NQO1 and GCLC." (PMID 33103077, 2020). "To test the role of NO on glutathione, we incubated human hepatocellular carcinoma derived Huh7 cells with NO donor S-nitroso-N-acetylpenicillamine (SNAP) versus vehicle (DMSO) control and observed a significant increase in mRNA expression of both GCL subunits, GCLC and GCLM." (PMID 38198573, 2024). "Moreover, studies have reported that GCLC mRNA levels and GSH expression levels were elevated in hepatocellular carcinoma cells, however, the expression of GCLM was not any altered in hepatocellular carcinoma cells." (PMID 40651948, 2025).
diabetes (10 papers, 2011 to 2025). "Polymorphisms of genes involved in diabetes pathogenesis, including IL8RA, TXN, NR3C2, COX5A, and GCLC, significantly modulated the association between urinary As levels and the odds of diabetes in a general Spanish population." (PMID 37624175, 2023). "The -129T allele variant in GCLC gene may cause susceptibility to MI, renal disease in patients with type 1 diabetes mellitus, schizophrenia, cystic fibrosis, chronic obstructive pulmonary disease, and nonalcoholic steatohepatitis in Brazilian patients." (PMID 28757675, 2017). "GCLC C/T+T/T genotypes were also associated with a significantly lower age at diabetes diagnosis (11 years old) in comparison to the C/C genotype (13 years old) (p = 0.0073) and with a higher frequency of use of angiotensin converting enzyme inhibitors (31.4% versus 18.8%, respectively; p = 0.0164)." (PMID 21962117, 2011). "CAV1 deficiency significantly attenuated diabetes-induced myocardial hypertrophy, fibrosis, oxidative stress, and cardiomyocyte ferroptosis and improved cardiac dysfunction by activating the NRF2/GCLC signaling pathway." (PMID 40303344, 2025). "We showed that inhibition of CAV1 alleviated diabetes-induced myocardial injury by activating NRF2/GCLC signaling." (PMID 40303344, 2025). "GCLc and GCLm are the main enzymes that catalyse glutathione synthesis, which has been shown to decline with the progression of various diseases, such as cancer, obesity, diabetes, neurodegenerative diseases, and age-related macular degeneration." (PMID 28146074, 2017). "For instance, no distinct GCLC expression pattern was appreciated in patients with and without a history of diabetes (n = 9 vs. 11)." (PMID 37380658, 2023). "We found that quercetin promoted the nuclear translocation of Nrf2 in cardiac cells of diabetic rats, increased the expression of the antioxidant proteins HO-1, GCLC, and SOD, reduced the accumulation of ROS and the degree of cardiomyocyte apoptosis, and alleviated diabetes-induced cardiac fibrosis." (PMID 36624860, 2022). "Moreover, western blot further confirmed total superoxide dismutase 1 (SOD1), heme oxygenase-1 (Hmox1) and glutamate cysteine ligase (GCLc) expression at protein level, supporting the hypothesis of PNS up-regulated antioxidants to ameliorate diabetes-induced oxidative stress." (PMID 37337262, 2023).